PTX3 (pentraxin 3)
Diseases named in the same sentence as PTX3 in open-access papers (continued):
Sharing a sentence is not in itself a finding about the gene and the disease.
Sepsis (continued). "The optimal cut-off value for PTX3 in predicting severe sepsis was 14.1 ng/ml (specificity 80% and sensitivity 63%), for PCT 0.30 ng/ml (specificity 66% and sensitivity 82%) and for CRP 158 mg/l (specificity 70% and sensitivity 47%)." (PMID 23341967, 2013). "The median PTX3 concentration was higher in severe sepsis patients compared to others (16.7 vs. 4.9 ng/ml, p<0.001) and in non-survivors (day 28 case fatality) compared to survivors (14.1 vs. 5.1 ng/ml, p<0.001)." (PMID 23341967, 2013). "PTX3 at a cut-off level for 14.1 ng/ml (optimal cut-off value for severe sepsis) showed 63% sensitivity and 80% specificity." (PMID 23341967, 2013). "PTX3 is an acute-phase protein whose plasma concentrations increases rapidly in various inflammatory conditions, including sepsis." (PMID 23341967, 2013). "The optimal PTX3 cut-off point for severe sepsis here was about the same as one would expect from earlier studies but the optimal cut-off for day 28 case fatality was surprisingly low, giving too low specificity for clinical work." (PMID 23341967, 2013). "The PTX3 serum concentration was significantly lower in the patients classified having SIRS only compared with those patients classified as having sepsis (Mann Witney, p<0.0001)." (PMID 24039869, 2013). "The results presented here show that high PTX3 levels on admission can be used to predict severe sepsis and case fatality in patients admitted to the emergency room with suspected infection." (PMID 23341967, 2013). "Because pentraxin 3 was identified as a component of NETs, the authors purify pentraxin 3 complexes from sepsis patients and carry out their proteomic analysis." (PMID 23805137, 2013). "In one previous study a high PTX3 has been shown to predict sepsis and severe disease in febrile patients admitted to emergency department." (PMID 23341967, 2013). "The median PTX3 was significantly higher in patients with severe sepsis as compared to others (16.7 vs. 4.9 ng/ml, p<0.001) and in non-survivors (day 28 case fatality) as compared to survivors (14.1 vs. 5.1 ng/ml, p<0.001)." (PMID 23341967, 2013). "A high PTX3 level on hospital admission predicts severe sepsis and case fatality in patients with suspected infection." (PMID 23341967, 2013). "In order to compare the performance of PTX3 with an established biomarker in SIRS and sepsis we compared PTX3 with CRP in the patients." (PMID 24039869, 2013). "In the case of sepsis, the plasma PTX3 dramatically increases to a level of up to 100 ng/mL and the increase correlates with mortality." (PMID 23248627, 2012). "Nevertheless, the disease-specific dynamics of these binding levels need to be investigated further, as do the specific functions of these PTX3 complexes in sepsis." (PMID 23248627, 2012). "In severe infectious diseases such as sepsis, the circulating PTX3 concentration increases greatly (up to 100 ng/mL, i.e., up to 100-fold of the normal level)." (PMID 23248627, 2012). "On the other hand, previous studies have shown that PTX3 is able to up-regulate tissue factor, a critical factor in the pathogenesis of coagulation/fibrinolysis dysregulation in sepsis." (PMID 21423699, 2011). "PTX3 has been studied as a biomarker in numerous studies on sepsis or septic shock." (PMID 40722110, 2025). "PTX3 may be used to evaluate sepsis intensity and aetiology, while CLU appears to be a more appropriate biomarker for mortality risk in this context." (PMID 40722110, 2025). "During febrile neutropenia in patients with haematological malignancies, pentraxin 3 (PTX3), a soluble innate immunity receptor, increases with severe sepsis, while clusterin, a chaperon protein involved in extracellular histones clearance, decreases in patients with quick SOFA score (qSOFA) ≥2." (PMID 40722110, 2025). "Both CRP and PTX3 levels increase during infection, particularly bacterial infections, and may be useful in predicting sepsis." (PMID 40722110, 2025).
Sepsis (continued). "Moreover, these variations differed significantly according to the sepsis severity groups studied, with a significantly higher elevation of PTX3 levels in group 3 than in group 1 (p = 0.009)." (PMID 40722110, 2025). "PTX3 levels increased in patients experiencing severe sepsis, irrespective of qSOFA, were associated with bacterial infections, and correlated with pro‐inflammatory cytokines and CRP." (PMID 40722110, 2025). "Therefore, the measurement of PTX-3 levels can assist healthcare professionals in promptly identifying and treating sepsis, offering valuable insights into the severity of the infection and the patient’s response to therapy." (PMID 39201697, 2024). "Furthermore, a prospective observational analysis highlighted the exceptional predictive performance of pentraxin 3 (PTX-3), IL-6, PCT, and lactate in predicting 28-day all-cause mortality in sepsis or septic shock patients, outperforming the SOFA score." (PMID 39130839, 2024). "While extensive evidence has demonstrated that PTX3 is expressed in several leukocytes, including monocytes, macrophages, dendritic cells, and neutrophils, in the context of infection and sepsis, studies in circulating blood for PTX3 levels in diabetes are inconclusive." (PMID 39348530, 2024). "In this study, we observed an increased level of PTX3 in the serum during sepsis." (PMID 39666228, 2024). "In summary, PTX3 inhibition can reduce LPS-induced liver injury through promoting hepatocyte ferroptosis and M1-type macrophage recruitment in sepsis, which suggests that PTX3 might be a novel regulator involved in the treatment of bacterial infections." (PMID 39666228, 2024). "This aims to offer a brief outlook for further research on the sepsis biomarker PTX-3." (PMID 39021820, 2024). "PTX3 functions as a key regulator in the inflammatory nexus of sepsis." (PMID 38784395, 2024). "Comparison of PTX-3 with other commonly used biomarkers in sepsis." (PMID 39021820, 2024). "In recent years, it has been found that the PTX-3 level increases sharply in the blood of sepsis patients, and may be superior to traditional biomarkers in judging the severity of their condition and prognosis assessment." (PMID 39021820, 2024). "The diagnostic value of IL-6 was superior to those of PTX3 and PCT for sepsis and septic shock." (PMID 36878489, 2023). "PTX3 is a soluble pattern recognition receptor with increased levels seen in sepsis and TB." (PMID 37616312, 2023). "Pentraxin-3 has been proven to be related to disease severity and worse outcomes in various diseases such as cancer, myocardial infarction, acute respiratory distress syndrome, and sepsis." (PMID 37510110, 2023). "PTX3 level could be used for survival prediction of patients who developed sepsis, and the predictive value of PTX3 for sepsis has been performed by using ROC curve analysis." (PMID 35676730, 2022). "In this survey, we measured PTX3 once, which may not be sufficient to conclude, and the authors recommend a longitudinal large-scale study to understand the exact role of PTX3 in sepsis development and other health consequences." (PMID 36168379, 2022). "A study found that deceased neonates with sepsis had considerably higher serum levels of PTX3 than survivors, suggesting that PTX3 could be utilised as a predictive biomarker for neonatal sepsis." (PMID 35449688, 2022). "Henceforth, novel biomarkers such as PTX3 in combination with lactate, PCT, and SOFA score might be helpful to improve the risk stratification of patients with sepsis." (PMID 36168379, 2022). "In addition, both molecules strongly correlated with SOFA score in sepsis and septic shock patients (PTX3: r=0.44, p<0.0001; sIL-1R2: r=0.35, p<0.0001), confirming data obtained in earlier studies, as well as with PCT, CRP and clinical parameters of severity." (PMID 36189302, 2022).
Sepsis (continued). "In a prospective observational analysis, PTX-3, IL-6, procalcitonin (PCT), and lactate combined showed excellent performance in predicting 28-day all-cause mortality among patients diagnosed with sepsis or septic shock and superior to the Sequential Organ Failure Assessment (SOFA) score." (PMID 34991675, 2022). "In recent years, PTX3 has emerged as a promising biomarker for sepsis." (PMID 35676730, 2022). "In addition, plasma levels of PTX3 have been reported to predict mortality in several systemic inflammatory conditions, including acute myocardial infarction and sepsis." (PMID 36389697, 2022). "It has been demonstrated that the level of PTX3 is elevated in patients with sepsis." (PMID 35676730, 2022). "Moreover, the ROC curve analysis indicated a good prognostic value of PTX3 in predicting mortality in patients with sepsis, and the AUC was related to both sample size and male proportion variables." (PMID 35676730, 2022). "Simple and multi-linear regression analyses were used to determine PTX3 as a predictor of sepsis." (PMID 36168379, 2022). "PTX3, in combination with established other markers, might improve the correlation with sepsis severity and needs to be studied." (PMID 36168379, 2022). "Therefore, we decided to conduct a survey to correlate serum PTX3 levels with the severity of sepsis." (PMID 36168379, 2022). "PTX3 as a biomarker of sepsis, and its diagnostic utility in northern Indian tertiary care setup, would help us evaluate the future scope in patients with sepsis." (PMID 36168379, 2022). "Studies conducted in neonates revealed that PTX3 is a good biomarker of early-onset sepsis." (PMID 35989325, 2022). "Many studies have analyzed PTX3 plasma levels in patients with sepsis." (PMID 35676730, 2022). "Consequently, the increase of serum PTX-3 levels in critically ill patients was correlated with the severity of the diseases from systemic inflammatory response syndrome to septic shock and sepsis." (PMID 33315349, 2021). "We have previously shown that the redox state of PTX3 and its oligomeric composition may serve as a marker of resolution of inflammation in patients with sepsis." (PMID 33288685, 2021). "We then analyzed PTX3 localization and distribution in our model of sepsis-induced AKI." (PMID 33868226, 2021). "In septic patients, both PCT and PTX3 have been associated with severity of sepsis, organ dysfunction, and higher mortality, but have not been studied in regard to dysglycemia." (PMID 33755703, 2021). "Higher levels of PTX3 were seen in non-survivors compared to survivors and were linked with the severity of sepsis." (PMID 34679604, 2021). "We aimed to conduct a prospective observational analysis to investigate the prognostic value of pentraxin 3, interleukin 6, procalcitonin, and lactate combined in predicting the 28-day mortality rate in patients with sepsis or septic shock (n = 160; sepsis, 78; sepsis shock, 82)." (PMID 32481464, 2020). "Neutrophils have been shown to release PTX-3 when activated in cardiovascular disease and sepsis." (PMID 32670996, 2020). "The octameric PTX-3 level in patients with sepsis could therefore be predictive of an unfavourable clinical state." (PMID 33425215, 2020). "Furthermore, several circulating molecules that take part in the inflammatory process in sepsis, including PTX3, showed altered levels in blood samples from patients with this syndrome." (PMID 33111742, 2020). "PTX-3 can be used as a prognostic biomarker in sepsis and septic shock in adults and children." (PMID 32244987, 2020). "Under normal physiological conditions, plasma PTX3 levels are low (<2 ng/mL) but increase rapidly in sepsis as a result of neutrophil degranulation—up to 100 ng/mL depending on the severity of disease —with levels maintained through de novo production by endothelial cells and some monocytic cells." (PMID 33301518, 2020).
Sepsis (continued). "We had previously investigated the diagnostic value of PTX3, IL6, and PCT individually in patients with sepsis or septic shock, where the results showed that each biomarker had good value in discriminating these patients from control patients who had no infections." (PMID 32481464, 2020). "In the present study, DEX increased TNF-induced PTX3 mRNA stability indicating the involvement of post-transcriptional mechanism as has been shown in mononuclear cells upon LPS stimulation in the context of sepsis." (PMID 31437159, 2019). "A recent study showed that PTX3 discriminated sepsis and septic shock patients from controls in a medical intensive care unit (ICU) in accordance with the Sepsis-3 definitions, suggesting that PTX3 has a diagnostic value comparable to that of IL-6 in sepsis and septic shock." (PMID 31718563, 2019). "The AUC of IL-6 to discriminate sepsis from the control group was 0.89 (95% confidence interval [CI], 0.97–1.00; P < 0.001), 0.84 for PTX3 (95% CI, 0.95–0.99; P < 0.001), 0.80 for PCT (95% CI, 0.86–0.96; P < 0.001), and 0.77 for CRP (95% CI, 0.71–0.91; P < 0.001)." (PMID 31718563, 2019). "As shown in a substudy of the ALBIOS trial, a multicenter, randomized controlled trial to compare the effect of human albumin and crystalloids versus crystalloids alone in patients with severe sepsis, PTX3-values had a tendency to decrease over time, even in cases of severe sepsis." (PMID 31798002, 2019). "In combination with other established biomarkers, PTX3 could improve stratification of sepsis patients and thus, complement the system of classification and monitoring of this disease." (PMID 31031772, 2019). "In contrast, during severe infections and sepsis PTX3 levels pass from 1–2 ng/ml to 100–600 ng/ml, suggesting that variations due to these factors are not a major limitation for the use of PTX3 as a biomarker in sepsis." (PMID 31031772, 2019). "Two patients died of sepsis, whose PTX3-levels were 2.5 ng/mL and 2.9 ng/mL." (PMID 31798002, 2019). "Several recent data demonstrate that PTX3, in combination with other established biomarkers, could be useful to improve stratification of patients with sepsis or septic shock." (PMID 31031772, 2019). "The results showed that serum IL-6 and PTX3 levels could identify the severity of sepsis (sepsis, septic shock, and controls) with optimal cut-off values." (PMID 31718563, 2019). "In a recent systemic review and meta-analysis, PTX3 was reported as a marker of sepsis severity and predictor of mortality; however, these results were drawn from sepsis diagnoses determined by the past Sepsis-2 definitions." (PMID 31718563, 2019). "In conclusion, this study confirmed in a large and controlled population that PTX3 levels are highly increased in severe sepsis and even more in septic shock, and that impaired normalization or reduction of PTX3 levels in the first days predicts multiorgan dysfunction and risk of mortality." (PMID 31031772, 2019). "Clinical studies reporting the use of PTX3 as biomarker of infectious diseases or sepsis/shock." (PMID 31031772, 2019). "Knowing that mature neutrophils are responsible for PTX3 secretion in the first hours of sepsis onset but are unable to produce de novo mRNA PTX3, we then aimed to decipher the cellular source of circulating PTX3 neo-synthesis in immunodysregulated septic shock patients." (PMID 30687307, 2018). "Altogether, these results indicate that sustained PTX3 plasma levels in the first week of sepsis could be driven by circulating blood cells, despite their altered immune functions." (PMID 30687307, 2018). "These cells are responsible for rapid and prompt release of PTX3 in inflammatory context, but the cellular origin responsible for successive days' elevation in sepsis remains unknown." (PMID 30687307, 2018). "Further experiments are required to evaluate this hypothesis to confirm if sustained circulating PTX3 levels in sepsis are achieved through this signaling pathway." (PMID 30687307, 2018).
Sepsis (continued). "In the present study we aimed to assess whether circulating cells could be responsible for the maintenance of PTX3 concentration in the blood of patients over time during severe sepsis." (PMID 30687307, 2018). "In conclusion, circulating PBMCs, despite their immune dysfunctions, could be responsible for the sustained PTX3 plasma levels over the first days of sepsis setting." (PMID 30687307, 2018). "Combining PTX-3 with established biomarkers, such as IL-6, might be of additional value for the discrimination of sepsis and septic shock." (PMID 28793880, 2017). "The ongoing systemic activation of inflammatory biomarkers such as CRP, interleukin-6 and PCT during sepsis and septic shock may be an explanation of their correlation with PTX-3 levels in affected patients." (PMID 28793880, 2017). "Although overall PTX-3 levels showed a decreasing linear trend from day 1 to day 8 of ICU treatment (p = 0.0001), median serum PTX-3 levels in patients with septic shock consistently remained higher than in patients with sepsis throughout the first week of ICU treatment." (PMID 28793880, 2017). "In contrast to previous studies, the present one aimed to evaluate the potential diagnostic value of PTX-3 in a real-life setting during the first week of treatment on a medical ICU, representing the most critical time frame of patients suffering from sepsis or septic shock." (PMID 28793880, 2017). "Furthermore, pentraxin 3 (PTX3) also exerts protective effects on sepsis, both in vivo and in vitro, due to its coaggregation with histones." (PMID 26609197, 2015). "This systematic review shows that although systemic levels of PTX3 are elevated in more severe forms of sepsis and bacteremia, its diagnostic value is low, as PTX3 is a nonspecific marker of inflammation." (PMID 25530683, 2014). "Also, in patients with suspected infection admitted to the emergency room, the AUC for prediction of severe sepsis between day 0 and day 28 was 0.73 for PTX3 (cut-off value 14.1 ng/m, sensitivity 63%, specificity 80%)." (PMID 25530683, 2014). "In earlier studies, the utility of PTX3 as a sepsis marker has been compared with CRP." (PMID 23341967, 2013). "Thus, we developed a novel assay for measurement of PTX3 in body fluids and examined the serum levels from patients with SIRS and sepsis admitted to an ICU as well as controls in order to review the validity of PTX3 as a biomarker in ICU patients." (PMID 24039869, 2013). "At a cut-off level 7.7 ng/ml (optimal cut-off value for case fatality) showed 70% sensitivity and 63% specificity in predicting case fatality on day 28.In multivariate models, high PTX3 remained an independent predictor of severe sepsis and case fatality after adjusting for potential confounders." (PMID 23341967, 2013). "This has also been shown in previous sepsis studies, and PTX3 may be involved in the pathological coagulation process in these conditions." (PMID 23341967, 2013). "PTX3 may be used to predict many variables indicating severe sepsis, i.e. need for ICU stay, hypotension, acute renal insufficiency and need for mechanical ventilation, already in the emergency room setting." (PMID 23341967, 2013). "AUCROC for prediction of severe sepsis was 0.73 (95% CI 0.66–0.81, p<0.001) for PTX3." (PMID 23341967, 2013). "Aim of the present study was to evaluate the usefulness of plasma PTX3 determination in early stratification and in predicting the development of severe sepsis and mortality in a large and unselected cohort of patients with suspected infection admitted to the emergency room." (PMID 23341967, 2013). "Even though it is clearly implied that PTX3 plays a protective role in sepsis and certain other disorders, the detailed mechanisms by which it does so remain unclear." (PMID 23248627, 2012). "Moreover, a potential role of PTX3 in the inflammatory response is suggested by elevated PTX3 levels in plasma of patients with sepsis, acute myocardial infarction, or chronic kidney disease." (PMID 22529962, 2012).